Y_RNA (Y RNA )
Gene: Miscellaneous RNA gene on chromosome X (50,171,197 to 50,171,297, reverse strand). Ensembl gene ENSG00000202495.
Homologues: Orthologues: chimpanzee Y_RNA (100% identical), macaque Y_RNA (92% identical), guinea pig Y_RNA (89% identical), pig Y_RNA (78% identical). Paralogues in human: Y_RNA (89% identical), Y_RNA (88% identical), RNY3 (87% identical), Y_RNA (87% identical), Y_RNA (86% identical), RNY3P16 (85% identical), Y_RNA (85% identical), RNY3P1 (84% identical), RNY3P2 (84% identical), Y_RNA (84% identical), Y_RNA (83% identical), RNY3P14 (82% identical), and 96 more.